HEXD (hexosaminidase D)
Description:
Has hexosaminidase activity. Responsible for the cleavage of the monosaccharides N-acetylglucosamine (GlcNAc) and N-acetylgalactosamine (GalNAc) from cellular substrates. Has a preference for galactosaminide over glucosaminide substrates.
Synonyms: HEXDC; FLJ23825
Tractability: Antibody: its Gene Ontology location is reachable by antibodies, with high confidence. PROTAC: ubiquitination databases record sites on it.
Target class: Enzyme; Hydrolase
Gene: Protein-coding gene on chromosome 17 (82,418,318 to 82,442,645, forward strand). Ensembl gene ENSG00000169660.
Subcellular location: Cytoplasm; Nucleus; Extracellular vesicle
Subcellular location (Human Protein Atlas): Mitochondria; Nucleoli fibrillar center
Gene Ontology:
Molecular function: beta-N-acetylhexosaminidase activity; hexosaminidase activity; hydrolase activity, hydrolyzing O-glycosyl compounds
Biological process: carbohydrate metabolic process
Cellular component: extracellular vesicle; cytoplasm; nucleus
Genetic constraint (gnomAD): Loss-of-function variants: 43 observed, 45.48 expected, observed/expected ratio (o/e) 0.95, 90% interval 0.74 to 1.22. The upper end of that interval is the gene's LOEUF score, 1.22, which puts it in group 5 of 6, group 1 being the genes least tolerant of losing a copy. Missense variants: 544 observed, 600.2 expected, observed/expected ratio (o/e) 0.91, 90% interval 0.84 to 0.97. Synonymous variants: 270 observed, 268.62 expected, observed/expected ratio (o/e) 1.01, 90% interval 0.91 to 1.11.
Homologues: Orthologues: macaque HEXD (94% identical), dog HEXD (81% identical), guinea pig HEXD (79% identical), mouse Hexd (79% identical), pig HEXD (78% identical), rat Hexd (78% identical), chimpanzee HEXD (77% identical), rabbit HEXD (75% identical), tropical clawed frog hexd (53% identical), zebrafish hexd (44% identical), Drosophila melanogaster CG7985 (38% identical), Caenorhabditis elegans hex-2 (30% identical), and 3 more.
Diseases named in the same sentence as HEXD in open-access papers:
HEXD is named in the same sentence as 1 disease in open-access papers, as found by Europe PMC text mining. Sharing a sentence is not in itself a finding about the gene and the disease. The quoted sentences say what the papers report.
rheumatoid arthritis (2 papers, 2020 to 2022). A chronic, systemic autoimmune disorder characterized by inflammation in the synovial membranes and articular surfaces. "Although the biological functions of its product, hexosaminidase D, remain largely unknown, it is believed to be a glycosidase and previous studies found associations with rheumatoid arthritis." (PMID 31931860, 2020).